PTPN18 (protein tyrosine phosphatase non-receptor type 18)
Diseases named in the same sentence as PTPN18 in open-access papers (continued):
Sharing a sentence is not in itself a finding about the gene and the disease.
low grade glioma (1 paper, 2023). A grade I or grade II glioma arising from the central nervous system. "We comprehensively analyzed the gene expression profiles from TCGA and GTEx, and observed that PTPN18 was highly expressed in some types of cancer, such as low-grade glioma (LGG) and GBM, compared with normal tissues." (PMID 36846716, 2023).
osteosarcoma (1 paper, 2019). A usually aggressive malignant bone-forming mesenchymal neoplasm, predominantly affecting adolescents and young adults.
triple-negative breast carcinoma (1 paper, 2022). An invasive breast carcinoma which is negative for expression of estrogen receptor (ER), progesterone receptor (PR), and human epidermal growth factor receptor 2 (HER2). "Given the downregulated expression of PTPN18 in triple-negative breast cancer cells, it can also be inferred that the degradation of ETS1 regulated by PTPN18 may be one of the reasons that ETS1 is only expressed in triple-negative breast cancer cells." (PMID 35982039, 2022).
tumor (7 papers, 2017 to 2026). "In addition, we found that PTPN18 was significantly correlated with tumor mutation burden (TMB) and microsatellite instability (MSI) in several cancers, indicating that PTPN18 may imitate cancer immunogenicity in these cancers." (PMID 36846716, 2023). "Moreover, PTPN18 prevented CD8+ T cells and M1 macrophages infiltrated into the lesion of tumor but accelerated Th17 cells and M2 macrophages infiltrating in to tumors." (PMID 36846716, 2023). "We analyzed the expression levels of PTPNs in the TCGA database and discovered that PTPN1, PTPN6, PTPN7, PTPN18, PTPN20, and PTPN22 were significantly upregulated in tumor samples, while PTPN4, PTPN5, PTPN10, PTPN11, PTPN13, PTPN14, and PTPN21 were downregulated in tumor samples." (PMID 36226189, 2022).
cancer (4 papers, 2022 to 2023). A tumor composed of atypical neoplastic, often pleomorphic cells that invade other tissues. "Our data showed that PTPN18 expression was involved in the cancer immunity cycle and negatively associated with multiple cycle stages." (PMID 36846716, 2023). "The enrichment analyses indicated that multiple cancer hallmark-related pathways varied notably between PTPN18 high and low groups, including immune response, intercellular signaling, metabolism, and other biological pathways." (PMID 36846716, 2023). "Consistent with the overall survival, PTPN18 demonstrated a significant association with cancer-specific survival in seven types of cancer, including LGG and GBM." (PMID 36846716, 2023). "To further explore the association between the expression of PTPN18 and antitumor immune response, we thoroughly inspected the immune-related genes with each cancer type." (PMID 36846716, 2023). "In the high PTPN18 group, activities of some steps in the cycle were downregulated, including cancer antigen presentation (step 2), priming and activation (step 3), and killing of cancer cells (step 7)." (PMID 36846716, 2023). "We previously performed the pan-cancer analysis of classical protein tyrosine phosphatases and confirmed that PTPN18 can inhibit breast cancer metastasis." (PMID 36846716, 2023). "The crucial role of PTPN18 in tumorigenesis and abnormal PTPN18 expression in different cancer was described in previous studies." (PMID 36846716, 2023). "The pan-cancer expression pattern of PTPN18 provoked us to investigate its predictive value." (PMID 36846716, 2023). "We explored the impacts of PTPN18 expression on the cancer immunity cycle." (PMID 36846716, 2023). "The function of PTPN18 in cancer is seemingly controversial in the literature." (PMID 35982039, 2022). "Thus, we speculated that the subcellular localization of PTPN18 may be one of the reasons for its contrasting role in different cancers." (PMID 35982039, 2022). "PTPN18 acts as a suppressor of EMT and cancer metastasis in pathological contexts." (PMID 35982039, 2022).
PTPN18 also shares sentences with these, for which no sentence is quoted: breast tumor (1 paper); hepatocellular carcinoma (1); lung carcinoma (1); ovarian carcinoma (1); Stroke (1).